MIF (macrophage migration inhibitory factor)
Diseases named in the same sentence as MIF in open-access papers (continued):
Sharing a sentence is not in itself a finding about the gene and the disease.
esophageal squamous cell carcinoma (11 papers, 2013 to 2026). Esophageal squamous cell carcinoma (ESCC) is a type of esophageal carcinoma (EC) that can affect any part of the esophagus, but is usually located in the upper or middle third. "The serum MIF level in patients with esophageal squamous cell carcinoma (ESCC) is associated with that of VEGF and vascular density in tumor tissue." (PMID 35842634, 2022). "In esophageal squamous cell carcinoma (ESCC), MIF drives cancer progression via Akt activation and GSK3β tumor suppressor inactivation." (PMID 38732068, 2024). "In this survey, we aimed to detect the expression levels of MIF and CXCR4 in different cell populations of tumor microenvironments and their association with survivals of patients with esophageal squamous cell carcinoma (ESCC)." (PMID 23497377, 2013). "Furthermore, there is a negative correlation between the amount of MIF and the effectiveness of PD‐1 blockade immunotherapy when used in conjunction with chemotherapy as a neoadjuvant treatment for esophageal squamous cell carcinoma." (PMID 39187937, 2024).
juvenile idiopathic arthritis (11 papers, 2010 to 2024). Juvenile idiopathic arthritis (JIA) is the term used to describe a group of inflammatory articular disorders of unknown cause that begin before the age of 16 and last over 6 weeks. "Previously, MIF was reported in association with susceptibility to juvenile arthritis, GSTT2 with S-phenylmercapturic acid levels in smokers, and USP2 suggestively with urate levels." (PMID 33137956, 2020). "Carriage of MIF −173 *C has also been found to be associated with an increased risk of adult inflammatory arthritis and juvenile idiopathic arthritis." (PMID 25821795, 2015). "It was therefore suggested that for juvenile idiopathic arthritis, the MIF-173C allele is a predictor of poor outcome." (PMID 22046508, 2010). "Consistent with that idea, circulating MIF levels were increased in individuals with juvenile idiopathic arthritis carrying the MIF-173C functional variant, and increased susceptibility to the disease was associated with carriership of either the MIF-173C or CATT allele." (PMID 22046508, 2010). "Patients with juvenile idiopathic arthritis and the MIF –173 C SNP have increased blood and synovial fluids MIF levels, which were predictive of a shorter duration of clinical response to corticosteroid therapy." (PMID 27598332, 2016). "MIF levels are increased in synovial fluid and synovial tissue from RA patients and patients with juvenile idiopathic arthritis." (PMID 22046508, 2010).
metabolic syndrome (11 papers, 2013 to 2025). A cluster of metabolic risk factors for CARDIOVASCULAR DISEASES and TYPE 2 DIABETES MELLITUS. "Development of metabolic syndrome is associated with impaired cardiac performance, mitochondrial dysfunction and pro-inflammatory cytokine increase, such as the macrophage migration inhibitory factor MIF." (PMID 23536817, 2013). "MVs isolated from plasma of metabolic syndrome patients have been identified as carriers of macrophage migration inhibitory factor (MIF)." (PMID 34123416, 2021). "Elevated serum MIF levels were described in obese female patients, suggesting a role for MIF as a potential contributor for the metabolic syndrome." (PMID 26348853, 2015). "In addition, MV isolated from plasma of obese patients and metabolic syndrome have been recently identified as specific carriers of Macrophage Migration Inhibitory Factor (MIF)." (PMID 33477341, 2021). "Therefore, we tested whether pharmacological inhibition of MIF prevented or worsened metabolic syndrome-induced myocardial dysfunction." (PMID 23536817, 2013).
metastatic melanoma (11 papers, 2014 to 2024). A melanoma that has spread from its primary site to another anatomic site. "Clinically, high MIF levels in metastatic melanoma were found to be associated with faster disease recurrence." (PMID 25168062, 2014). "Our results establish the concept that high MIF expression levels in metastatic melanoma is associated with faster relapse and death." (PMID 25168062, 2014). "While CD74 typically acts as a chaperone for MHC molecules under normal conditions, it gets targeted by MIF in metastatic melanoma, altering its immunogenic role and reducing the DCs’ ability to expand antitumor CD8 + T cells." (PMID 38777826, 2024). "In cutaneous metastatic melanomas, the fact that MIF suppresses immunogenicity adaptive responses by targeting macrophages (MOs) and DCs through the CD74 receptor is a crucial realisation." (PMID 37454231, 2023). "The use of MIF receptor antagonists led to a significant reduction in the number of Tregs in metastatic melanoma tissues in mice, indicating that MIF promotes tumor development via effects on Tregs." (PMID 35842634, 2022). "More recent studies revealed that MDSC-derived autocrine MIF is necessary for maximal immunosuppression of primary M-MDSCs isolated from the peripheral blood of stage III-IV metastatic melanoma patients." (PMID 33324425, 2020). "Nevertheless, MIF expression can only be used as a prognosis marker in the case of metastatic melanoma." (PMID 31013837, 2019). "In conclusion, our findings suggest that MIF is highly secreted in metastatic melanoma and is an important immunosuppressor of MOs and DCs." (PMID 29875777, 2018). "Since the levels of MIF differed between primary and metastatic melanoma, analyses were conducted on each classification where tumour biopsies were initially segregated into quartiles of MIF expression ranging from low to high values." (PMID 25168062, 2014). "Analysis of average levels in each group showed a statistically higher level of MIF in metastatic melanoma compared to primary tumour samples." (PMID 25168062, 2014). "MIF not only suppresses DCs maturation and activation but also significantly impairs their ability to activate cytotoxic T cells killing function, facilitating metastatic melanoma progression." (PMID 35842634, 2022). "However, the role of MIF in metastatic melanoma remains unclear." (PMID 29875777, 2018). "MIF/CD74 activity promotes immunosuppressive signaling in macrophages and dendritic cells and inhibition of this signaling re-establishes the antitumor immune response in metastatic melanoma." (PMID 36496973, 2022). "Blocking MIF signaling through CD74 on MOs and DCs, using the C36L1 Ig-CDR-based peptide, restores the pro-inflammatory functions of MOs and DCs thereby harnessing the immune response against metastatic melanoma." (PMID 29875777, 2018). "Although this study was originally grounded on the rationale that MIF/CD74 axis drives poor immunogenicity in metastatic melanoma, a significant limitation of this study is the lack of functional validation for the hypoxia-related results in MIF/CD74 dependent signalling." (PMID 37454231, 2023). "In this context, our review highlights that MIF could be a target of choice in metastatic melanoma treatment, where there is a significant lack of therapies after the development of resistance to targeted and immunotherapies." (PMID 31013837, 2019). "Blocking specific mechanisms of immunogenicity suppression, such as MIF/CD74 in metastatic melanoma, as opposed to a ‘shotgun’ approach of promoting more GM-CSF expression to increase overall immune activity, could offer a more precise, efficient, and potentially less toxic therapeutic route." (PMID 37454231, 2023).
acute coronary syndrome (10 papers, 2012 to 2024). Signs and symptoms related to acute ischemia of the myocardium secondary to coronary artery disease. "We investigated an association between the polymorphism of MIF gene rs2070766 and acute coronary syndromes (ACS) and the predictive value of MIF gene variation in clinical outcomes." (PMID 35046995, 2021). "This study determined the association between polymorphisms of MIF gene and acute coronary syndrome (ACS)." (PMID 31924846, 2020). "In another study, the 6,7 genotype of the MIF −794 CATT5–8 polymorphism was associated with susceptibility to acute coronary syndrome in a western Mexican population." (PMID 25972622, 2015). "In clinical studies, elevated plasma MIF levels in patients with acute coronary syndrome also correlated with increased inflammatory markers such as C-reactive protein (CRP) and IL-6." (PMID 24098445, 2013).
cystitis (10 papers, 2006 to 2024). Inflammation of the urinary bladder. "Macrophage migration inhibitory factor (MIF), a pleiotropic pro-inflammatory cytokine found in many different cells (including urothelium), is associated with experimental cystitis and urinary tract infection in humans." (PMID 19503733, 2009). "Such associations, if present, would indicate another possible receptor target for MIF during cystitis, aside from the already described MIF-CD74 association." (PMID 19066630, 2008). "Many investigators have also noted the presence of MIF in the urothelium and the role of MIF in cystitis; therefore, MIF appears to be related to bladder inflammation." (PMID 25705692, 2015). "Previous studies have focused on the use of elevated urinary MIF levels to detect the presence of UTIs and to distinguish kidney infections from acute cystitis." (PMID 23319831, 2012). "During cystitis, MIF is upregulated in the bladder, released from the bladder, and detected in the urine as a potential marker for cystitis." (PMID 23319831, 2012). "Understanding the triggers evoking urothelial MIF release is an important component of understanding how cystitis is developed or maintained." (PMID 21209875, 2010). "We have demonstrated that released MIF is pro-inflammatory since blocking MIF or receptors for MIF reduce morphological and physiological signs of cystitis as well as decrease bladder production of pro-inflammatory cytokines, including MIF." (PMID 21209875, 2010). "MIF is released (complexed to other proteins) into the lumen during cystitis and this process depends on activation of bladder afferent and efferent nerves." (PMID 19503733, 2009). "Examining changes in urothelial MIF content and also changes in inflammatory markers in the urothelium would answer questions about the source of released MIF during cystitis and would also support an active role for the urothelium during inflammation." (PMID 19503733, 2009). "MIF, CD74, and CD44 are all upregulatedduring experimental bladder inflammation suggesting that MIF-mediated signalingmay be involved in cystitis." (PMID 19325914, 2009). "We have been studyingthe role of a unique proinflammatory cytokine, macrophage migration inhibitoryfactor (MIF) in experimental and clinical cystitis." (PMID 19325914, 2009). "Taken together, our results show that preventing MIF from binding to specific urothelial receptors reduces or prevents cystitis." (PMID 19503733, 2009). "Thus, our current and past experimental observations indicate that MIF likely plays a pivotal role in mediating bladder pain, at least in experimental models of bladder pain and cystitis." (PMID 27010488, 2016). "Thus, during cystitis not only is there MIF released into the lumen but also expression of receptors on the surface of urothelial cells that bind to MIF to maintain or promote bladder inflammation." (PMID 19503733, 2009). "Furthermore, cystitis (e.g. experimental in rats or bacterial in humans) increased levels of MIF in the intraluminal fluid (or urine) and upregulated MIF production in the bladder." (PMID 16981995, 2006). "While PAR activation, particularly by PAR1 and PAR4, is not directly causative of cystitis in the urothelium, it contributes to the disease progression through the mediation of macrophage migration inhibitory factor (MIF), at least in part through activation of CXCR4 receptors." (PMID 39201414, 2024). "In CYP-induced cystitis in the rat increased levels of MIF occur in the urine and MIF can also be detected in all areas of the urothelium, not only in the basal part as is the case in healthy bladders." (PMID 24982868, 2014). "Macrophage migration inhibitory factor (MIF) is a pro-inflammatory cytokine involved in cystitis and a non-cognate ligand of the chemokine receptor CXCR4 in vitro." (PMID 19066630, 2008).
cystitis (continued). "In CYP-induced cystitis, then, activation of CXCR4 receptors, either by its recognized ligand SDF-1 (upregulated as a result of CYP) or due to interaction with MIF (also upregulated as a result of CYP and present in greater quantities than SDF-1) may in fact be contributing to pain hypersensitivity." (PMID 19066630, 2008).
dementia (10 papers, 2017 to 2025). Loss of intellectual abilities interfering with an individual's social and occupational functions. "Our findings are consistent with previous studies, showing that increased MIF protein expression in the DLPFC of individuals with dementia." (PMID 41282231, 2025). "Despite most of these being more prominently dysregulated in AD (e.g., SDC4, ITGB2, MIF, and sTREM1), a small subset of proteins showed an opposite effect between these dementias (e.g., CHL1, GPC1, and CNTN5)." (PMID 40866991, 2025). "MIF expression was significantly increased in individuals with a clinical diagnosis of AD dementia (p = 0.02) compared to non-cognitively impaired individuals, matching the increased proportion of CD74high microglia observed in individuals with dementia." (PMID 41282231, 2025). "Excess MIF has been documented in CSF of patients clinically diagnosed with amnestic MCI and mild AD, suggesting that MIF could play a role in the pathogenesis of AD at the pre-dementia and early dementia stages." (PMID 32303185, 2020). "This was indicative that MIF release could be a defense mechanism by neurons, and that was how AD is distinguished from other types of dementia, such as VD." (PMID 31174614, 2019). "Taken as a whole, these data indicate increased MIF production in AD and MCI, suggesting that MIF may be involved in the occurring neuroinflammatory process at a clinical pre-dementia disease stage." (PMID 31936865, 2020). "In summary, we found that the upregulation of MIF expression specifically occurs in patients with AD rather than other types of dementia and identified that the level of MIF in CSF could serve as a biomarker of AD with global inflammation." (PMID 31174614, 2019). "Interestingly, MIF level was not elevated in patients with VD, indicating the elevation of MIF in the CSF possibly is specific to patients with dementia due to AD." (PMID 31174614, 2019).
liver cancer (10 papers, 2017 to 2025). An epithelial or non-epithelial malignant neoplasm that arises from the liver. "This suggested that tumor cells primarily affected the functions of most immune cells through the MIF signaling pathway, thereby influencing the occurrence of tumors and the survival status of patients with liver cancer." (PMID 40018995, 2025). "The potential biological processes mediated by MIF in liver cancer are revealed, with RNA splicing notably highlighted." (PMID 40881277, 2025). "This study evaluates the role of MIF in liver cancer from a unique perspective based on TIL-related genes." (PMID 40881277, 2025). "From serum MIF diagnosis, fifty-three patients had positive results for primary liver cancer, of which eight had false positive results, with a sensitivity of 84.91%, a specificity of 78.38%, and an accuracy of 82.22%, respectively." (PMID 34475930, 2021). "Large sample size is required to confirm the diagnostic value of 5 serological tumor markers such as MIF and GP73 for primary liver cancer, so as to provide more effective guidance for clinical diagnosis." (PMID 34475930, 2021). "Serum MIF for the diagnosis of primary liver cancer had a sensitivity of 84.91%, a specificity of 78.38% and an accuracy of 82.22%." (PMID 34475930, 2021). "Fifty-three patients were diagnosed as positive for primary liver cancer from serum MIF, of which eight had false positive results." (PMID 34475930, 2021). "Studies show MIF presence in the sera after hepatic resection or expression in the course of liver cancer progression." (PMID 31102112, 2019). "When recombinant MIF (rMIF) was expressed in human liver cancer cells, an increase in cytoplasmic LC3-I to LC3-II conversion was observed." (PMID 28753959, 2017). "Given that MIF acted as a macrophage stimulator, we speculate from cell communication results that PPP1R16A cells may promote macrophage aggregation through the MIF pathway, which inducing M2 polarization of liver cancer cells." (PMID 39010084, 2024). "In addition, inhibition of MIF expression via shRNA resulted in a reduction in autophagy in liver cancer cells." (PMID 28753959, 2017). "Serum MIF, GP73, PIVKA-II, AFP-L3 and AFP all have certain diagnostic value for primary liver cancer; the combined detection of five serological tumor markers can significantly improve the sensitivity, specificity and accuracy of the diagnosis of primary liver cancer, with higher diagnostic value." (PMID 34475930, 2021). "Both MIF (macrophage migration inhibitory factor) and CD74 (CD74 molecule) were found spatially expressed and distributed in many tumor tissues, including liver cancer, intestine injured tissue and pancreas." (PMID 36243975, 2023). "Additionally, scRNA-seq analysis revealed the roles of different cell types in liver cancer, identifying T cells as key players in the TIL pathway, primarily mediating intercellular communication via the MIF signaling pathway." (PMID 40881277, 2025). "In this study, the levels of MIF, GP73, PIVKA-II, AFP-L3 and AFP in serum were examined, aiming to investigate its application value in diagnosing primary liver cancer and provide a new direction for the clinical diagnosis and treatment of primary liver cancer." (PMID 34475930, 2021).
lung disease (10 papers, 2014 to 2024). "Recent studies have identified WISP1 and Macrophage Migration Inhibitory Factor (MIF) as two candidate molecules implicated in the pathophysiology of lung diseases." (PMID 39337534, 2024). "MIF is associated with lung disease severity in CF, decreasing promoter activity, and is associated with a slower decline in lung function." (PMID 40225935, 2024). "The convincing evidence on the effective role of MIF in the pathophysiology of developmental neonatal lung diseases are limited." (PMID 33356032, 2021). "In conclusion, we have provided additional independent data supporting the role of MIF as a modifier gene of lung disease in CF; the beneficial effect, however, was limited to the homozygous genotype displaying the lowest transcriptional activity." (PMID 25503271, 2014). "Its impact on HLFs goes beyond MIF, including the stimulation of COX-2, IL-6, and MMP-2 expression, along with the synthesis of PGE2 implicated in inflammation and remodeling of the ECM, processes that play significant pathogenetic roles in lung diseases." (PMID 38145300, 2024). "Importantly, in a recent study, we have highlighted the interplay between WISP1 and MIF in lung diseases." (PMID 39337534, 2024). "In conclusion, the implication of WISP1 in the pathophysiology of various lung diseases may be mediated, at least in part, by the increased expression of MIF and its stimulatory effect on the production of established pathogenetic effectors." (PMID 38145300, 2024). "MIF controlled the production of other cytokines such as IL-1β, IL-6, IL-8 and TNF-α in neonatal lung diseases." (PMID 33356032, 2021). "If this is the case, αvβ5-integrin could be proved to be an ideal target for the treatment of various lung diseases where fibroblasts, WISP1, and MIF play critical pathogenetic roles." (PMID 38145300, 2024). "Although WISP1 and MIF are present in lung tissue and both play a role in the development of various lung diseases, their interrelationship has not been established yet." (PMID 38145300, 2024).